HGF (hepatocyte growth factor)
Diseases named in the same sentence as HGF in open-access papers (continued):
Sharing a sentence is not in itself a finding about the gene and the disease.
rheumatoid arthritis (13 papers, 2012 to 2026). A chronic, systemic autoimmune disorder characterized by inflammation in the synovial membranes and articular surfaces. "Clinical research indicated combing Lugua polypeptides (鹿瓜多肽) with UC-MSCs improved rheumatoid arthritis (RA) outcomes by significantly increasing HGF expression." (PMID 40999449, 2025). "Previous studies showed its expression in the synovium of rheumatoid arthritis and osteoarthritis patients and that inhibition of HGF suppressed progression of arthritis and bone destruction in SKG mice." (PMID 37810213, 2023). "Except for one report, HGF/DPSCs and DPSCs were confirmed to possess an equal therapeutic effect on rheumatoid arthritis in mice within the first 41 days." (PMID 35922965, 2022). "In the early phase of rheumatoid arthritis progression, HGF overexpression in hDPSCs inhibited pathological aggression by its immunosuppressive effects." (PMID 33933140, 2021). "In the late phase of rheumatoid arthritis, HGF promoted synovitis by activating fibroblast-like synoviocytes to produce pathogenic IL-6, which accelerated cell proliferation and induced apoptosis resistance." (PMID 33933140, 2021). "Previous research on patients with rheumatoid arthritis (RA) have demonstrated elevated HGF levels in serum, synovium, synovial fluid and joint adipose tissue, and that above-median levels of plasma HGF predicted progress in radiographic joint damage." (PMID 40410839, 2025). "recently discovered that pulp stem cells overexpressing HGF have dual effects in rheumatoid arthritis (RA)." (PMID 34970484, 2021). "However, HGF-modified DPSCs have dual role in rheumatoid arthritis (RA)." (PMID 32522231, 2020). "We previously demonstrated that blocking hepatocyte growth factor (HGF) receptor/c-Met signaling inhibited arthritis and articular bone destruction in mouse models of rheumatoid arthritis (RA)." (PMID 25941631, 2015). "We previously demonstrated that blocking the hepatocyte growth factor (HGF) receptor, c-Met, using a HGF antagonist, NK4, inhibited arthritis in a rheumatoid arthritis (RA) model mice." (PMID 25332857, 2014).
steatosis (13 papers, 2016 to 2024). Increased lipid within the cytoplasm of cells. "While in mild fibrosis, steatosis was associated with decreased HGF and VEGF levels, in advanced fibrosis, HGF was increased in patients with steatosis." (PMID 39200991, 2024). "Our results contrast with the reported effects of acute treatment with recombinant, active HGF in rodents to reduce steatosis and with inconsistent effects on circulating triglycerides." (PMID 36413406, 2023). "Yet, paradoxically, recent reports suggest that activation of c-MET pathway by HGF supplementation alleviates steatosis." (PMID 34944593, 2021). "In short, the deletion of cMET and hampering of the HGF/cMET axis leads to the development of steatosis." (PMID 34944593, 2021). "The HGF/c-Met signaling pathway prevents from steatosis development and has a protective function in the progression to steatohepatitis and fibrosis." (PMID 30538805, 2018). "Additionally, marked and sustained transgenic overexpression of HGF under a metallothionein promoter reduced steatosis, in contrast with our observations." (PMID 36413406, 2023). "In the more relevant clinical model of NAFLD, HGF and EGF have both been reported to alleviate steatosis, by facilitating release of lipids from hepatocytes to the blood." (PMID 33504774, 2021). "Single injections of either HGF or EGF mRNA-LNP decreased steatosis, although combination of both mRNA-LNP consistently resulted in significantly more efficient steatosis reversion assessed with serum cholesterol levels and Oil Red O staining." (PMID 33504774, 2021). "In a chronic liver injury mouse model recapitulating non-alcoholic fatty liver disease, injections of both HGF and EGF mRNA-LNP sharply reverse steatosis and accelerate restoration of liver function." (PMID 33504774, 2021). "On the contrary, HGF levels significantly increased in patients with steatosis but not in non-steatotic patients." (PMID 39200991, 2024). "Next, we evaluated whether, in addition to the benefits in terms of APT, glycogen and phospholipids induced by the lipid treatment in steatotic livers, changes in growth factors (HGF, IGF1 and VEGFA) could explain the enhanced benefits conferred by the lipid treatment in the presence of steatosis." (PMID 34444713, 2021). "However, a second injection of HGF/EGF mRNA-LNP significantly released cholesterol into the serum, diminished steatosis, and decreased serum ALT levels at T8, suggesting that a repeated regimen of HGF/EGF mRNA-LNP injections could alleviate chronic liver damage." (PMID 33504774, 2021). "The plasma level of NT‐3, CCL20, CCL4, CCL3, LIF‐R, OPG, and HGF was higher, and SCF was lower only in the severe steatosis versus no steatosis." (PMID 35128832, 2022).
ulcer (13 papers, 2008 to 2025). "Recently, we demonstrated that a CM of an immortalized stem cell line from human exfoliated deciduous teeth (SHED) has protective effects against a mouse model of ulcer formation via antioxidative and angiogenic activities mediated by HGF and VEGF." (PMID 39857443, 2025). "It referred the published clinical data which suggest that HGF plasmid was beneficial for improvement of pain and ulcer size in critical limb ischemia patients, although the population was small." (PMID 36826582, 2023). "Other clinical trials concluded that different routes of administration or doses of HGF plasmid also resulted in an improvement of ulcer healing and reducing rest pain." (PMID 36826582, 2023). "To date, three randomized placebo-controlled clinical trials using naked human HGF plasmid DNA proved its beneficial effect in the healing of ulcers, decrease in rest pain, and increase in trans-cutaneous oxygen tension." (PMID 29601487, 2018). "All these factors, especially the modulation of the NOS-pathway helped in upregulating mucosal VEGF and HGF levels to promote angiogenesis and accelerate ulcer healing." (PMID 22966242, 2012). "Despite high HGF levels in chronic ulcers, up-regulation of HGF receptor in ulcer tissue and decreased biological activity of HGF in ulcer secretions have been observed." (PMID 18569024, 2008). "The re-epithelialization and development of granulation tissue at the ulcer base are modulated by the release and interactions of growth factors (i.e. epidermal growth factors, hepatocyte growth factor, transforming growth factorsα/β and vascular endothelial growth factor)." (PMID 29095895, 2017). "The ulcer was treated conservatively with the local application of an antibiotic gel containing 250 mg vancomycin and hepatocyte growth factor (HGF in 100 IU antithrombin III Baxter) plus sodium chloride for 2 days, followed by antithrombin III plus sodium chloride gel for 5 days." (PMID 27502024, 2016). "The long-term efficacy of HGF gene therapy with an increase in ABI, and a reduction of rest pain and ulcer size 2 years after gene therapy has also been demonstrated." (PMID 29601487, 2018). "Notably, we observed increased fibroblast-to-immune signaling through the midkine (MK), hepatocyte growth factor (HGF), IGF-binding protein (IGFBP), and KIT (stem cell factor) pathways in GK-high ulcers." (PMID 41583446, 2025). "Also in a randomized, double-blind, clinical trial in patients with serious PAD of Fontaine stage III/IV who could not undergo revascularization with HGF plasmid, rest pain and ulcer size significantly decreased in the HGF group in comparison with those in the control group." (PMID 24350247, 2013).
amyotrophic lateral sclerosis (12 papers, 2011 to 2024). Amyotrophic lateral sclerosis (ALS) is a neurodegenerative disease characterized by progressive muscular paralysis reflecting degeneration of motor neurons in the primary motor cortex, corticospinal tracts, brainstem and spinal cord. "The phase-I and phase-I/II clinical trials of the intrathecal administration of HGF protein for the treatment of patients with amyotrophic lateral sclerosis and spinal cord injury, respectively, are ongoing." (PMID 28548072, 2014). "Clinical trials using the HGF protein for the treatment of patients, including those with fulminant hepatitis, spinal cord injury, amyotrophic lateral sclerosis (ALS), and vocal fold scarring, have been completed or are ongoing." (PMID 33121208, 2020). "Studies in animal models of neurodegenerative diseases such as MS, Alzheimer’s disease, amyotrophic lateral sclerosis (ALS), cerebral ischemia, and spinal cord injury (SCI) have also demonstrated the beneficial effects of HGF." (PMID 39457044, 2024).
astrocytoma (12 papers, 2012 to 2025). "Malignant astrocytomas are associated with HGF overexpression." (PMID 33066121, 2020). "Despite variability in HGF abundance, the incredible magnitude of HGFR expression suggests that the HGF/HGFR signaling axis is relevant in canine astrocytoma pathogenesis." (PMID 34131649, 2021). "In addition, expression levels of HGF and its receptor cMet correlate with astrocytoma grade." (PMID 22966858, 2012). "Several of these genes, including MYC, EGFR, HIF1A, HGF, APOE, TIMP3, and WNT5A have been identified as being important to development of astrocytoma." (PMID 23737970, 2013). "In astrocytoma cells, TGF-β family ligands decrease HGF synthesis and secretion." (PMID 29238047, 2017).
endometrial cancer (12 papers, 2010 to 2025). Primary or metastatic malignant neoplasm involving the endometrium (mucous membrane that lines the endometrial cavity). "In turn, IL-6 and TNF-α induce the stromal expression of hepatocyte growth factor (HGF) which in turn stimulates endometrial cancer invasion." (PMID 34951691, 2022). "Addition of hepatocyte GF (HGF) neutralizing antibody or HGF inhibitor NK4 inhibited estradiol-induced endometrial cancer cell invasion, which suggests that HGF treatment increases estradiol-induced invasiveness of endometrial cancer cells." (PMID 34951691, 2022). "This notion was supported by our experiments in the endometrial cancer cell line, which showed that HGF induced delayed c-MET phosphorylation, accompanied by rapid dephosphorylation." (PMID 34439385, 2021). "The overexpression of Met, the receptor for HGF, has been reported in many cancers of epithelial cell origin, including endometrial cancer." (PMID 29854314, 2018). "In a previous report, we investigated the HGF/Met signaling pathway in endometrial cancer cell lines." (PMID 29854314, 2018). "In the present study, the HGF/Met-MAPK/PI3K pathway in endometrial cancer cell lines was activated by HGF in an autocrine manner." (PMID 29854314, 2018). "We evaluated the HGF/Met signaling pathway in endometrial cancer cell lines and assessed the anti-cancer effects of foretinib using in vitro and in vivo experimental models." (PMID 29854314, 2018). "HGF/Met signaling in endometrial cancer cell lines was stimulated in an autocrine manner, and was essential for cell survival." (PMID 29854314, 2018). "Migration-Inducting Gene 7 (MIG-7) is a cysteine-rich protein first identified in endometrial cancer cells upon hepatocyte growth factor (HGF) treatment." (PMID 27050277, 2016). "The HGF/Met-MAPK/PI3K pathway in endometrial cancer is activated by HGF in an autocrine manner." (PMID 29854314, 2018). "In addition, a recent report based on HEC-1B and RL95-2 (two human endometrial cancer cell lines) showed that the treatment of these cells with hepatocyte growth factor (HGF) led to an up-regulation of COX-2." (PMID 20339581, 2010). "The main cytokines secreted by CAFs isolated from human endometrial cancer tissue include MCP-1, CCL5, RANTES, interleukin-6, and -8 (IL-6, IL-8) VEGF, EGF, HGF, FGF-2, as well as TGFβ1 isoform." (PMID 34501347, 2021). "As demonstrated, molecules secreted by CAFs, i.e., TGFβ1, EGF, HGF, and FGF-2, potentiate the migration and invasion of endometrial cancer cells (RL-952) when administered exogenously, thus inducing lung metastasis in vivo in mouse subcutaneous xenograft assay." (PMID 34501347, 2021). "Hepatocyte growth factor (HGF), also produced by stromal endometrial cells, supports the growth and proliferation of epithelial and stromal cells in the endometrium, and unregulated HGF/c-MET/Akt pathway activation is even shown to drive carcinogenesis in endometrial carcinoma." (PMID 40628401, 2025). "Whether secretion of growth factors (TGFβ, GAS6, FGF5 and HGF), cytokines and chemokines (IL-6, CXCL9) from CAFs,32 may affect aggressiveness and thereby associate with recurrence of endometrial cancer, is not known and could be investigated in future studies." (PMID 37146405, 2023).
invasive breast carcinoma (12 papers, 2007 to 2021). A carcinoma that infiltrates the breast parenchyma. "Expression of matriptase (an activator of HGF) is positively correlated with both c-Met and HGF in invasive breast cancer, and high levels of c-Met and matriptase are associated with reduced 30-year survival at univariate analysis." (PMID 25887320, 2015). "Previous studies have linked HGF/MET signaling with poor outcome in invasive breast cancers." (PMID 24025166, 2013). "HGF and c-Met are frequently coexpressed in invasive breast cancers: c-Met in epithelial cells and HGF in epithelial cells (autocrine pattern) and/or stromal cells (paracrine pattern)." (PMID 25887320, 2015). "Previous studies demonstrated that higher HGF levels were found in patients with invasive breast cancer compared to controls." (PMID 24982892, 2014). "HGF is the only known ligand for cMET, and the HGF/cMET signaling pathway has long been studied in normal development, ductal morphogenesis, invasive breast cancer, and invasive biology of several other cancers due to its angiogenic, mitogenic, and morphogenic effects." (PMID 27057482, 2016). "Likewise, forced overexpression of HGF or TGF-β in human mammary fibroblasts can induce human mammary epithelia to develop outgrowths indistinguishable from invasive breast carcinomas." (PMID 25880005, 2015).
mesothelioma (12 papers, 1998 to 2023). A usually malignant and aggressive neoplasm of the mesothelium which is often associated with exposure to asbestos. "Other angiogenesis-related factors, such as fibroblast growth factor-2 (FGF-2) and hepatocyte growth factor (HGF), are hyper-expressed in mesothelioma, at 50% and 85%, respectively." (PMID 29342862, 2018). "The clinical study can also provide information regarding production of NK4 protein and antibody against NK4, and inhibition levels of the HGF/c-Met pathway by detecting dephosphorylation of c-Met in mesothelioma cells." (PMID 26191485, 2015). "Transduction of mesothelioma with Ad-NK4 inhibited HGF-mediated phosphorylation of c-Met and the cell migration." (PMID 26191485, 2015). "Taken together, it was found that the defect of poly(dA) in the HGF promoter was present in various types of cancer, including lung, stomach, colorectal, pancreas and mesothelioma." (PMID 25436000, 2015). "Co-expression of HGF and its receptor was also observed in mesothelioma specimens, indicating a role for HGF/Met signaling in the development of this tumor, either by autocrine or paracrine mechanisms." (PMID 28548074, 2014). "In mesothelioma cells cultured on collagen type IV, HGF induced morphological changes with protrusion of prominent pseudopodia and acquisition of bipolar shape." (PMID 28548074, 2014). "Preclinical studies to inhibit the HGF/c-Met pathways with gene medicine were conducted for mesothelioma." (PMID 23484132, 2013). "Akt is also a redox-sensitive target for oxidant and growth factor stimulation, such as hepatocyte growth factor and its receptor tyrosine kinase, c-Met, which are highly expressed in mesotheliomas through the activation of PI-3K/Akt pathway." (PMID 18795165, 2008). "The results show a predominant role for HGF/SF in mesothelioma cell invasion, stimulating simultaneously adhesion, motility, invasion and regulation of MMP and TIMP levels." (PMID 11027427, 2000). "We show here that exogenous HGF/SF acts as a strong chemoattractant for human mesothelioma cell lines." (PMID 11027427, 2000). "The expression of hepatocyte growth factor/scatter factor (HGF/SF) was studied in 12 mesothelioma cell lines characterized by either an epithelioid or a fibroblast-like phenotype." (PMID 9569039, 1998). "The hepatocyte growth factor (HGF)/c-Met signal pathway is up-regulated in human mesothelioma and suppression of the HGF/c-Met signaling with a competitive inhibitor, NK4 homologous to HGF in the structure, produced anti-tumor effects to mesothelioma in a preclinical study." (PMID 26191485, 2015). "Clinical outcomes by Ad-NK4 administration will be influenced by dependence levels of mesothelioma on the HGF/c-Met pathway for the cell growth and on the angiogenesis which is produced by interactions between the tumors and the surrounding interstitial tissues." (PMID 26191485, 2015). "Furthermore, an expression level of hepatocyte growth factor (HGF) and the receptor, c-Met, is also augmented in a majority of mesothelioma specimens." (PMID 26191485, 2015). "Moreover, Met expression was found in cells obtained from pleural fluids of patients with mesothelioma, while HGF resulted mitogenic for mesothelial cells." (PMID 28548074, 2014). "In addition, effects of protease inhibitors on invasion suggested that serine proteases were also expressed in human mesothelioma cell lines and were involved in HGF/SF-induced invasion." (PMID 11027427, 2000). "It is a concern that factors previously reported as being secreted by MPM cells, such as FGF2, HGF, PDGF-AA and VEGF validated poorly across patient-derived and commercial mesothelioma cell lines in our study." (PMID 37938546, 2023). "Biochemical analyses showed that 3 major signaling pathways were activated in mesothelioma, EGF and EGFR, VEGF and the receptors VEGFR1 and VEGFR2, and hepatocyte growth factor (HGF) and the receptor c-Met." (PMID 23484132, 2013).
mesothelioma (continued). "Furthermore, FGF2 leads to fibroblast production of hepatocyte growth factor (HGF) and platelet-derived growth factor A (PDGF-A) which can in turn stimulate the growth and migration of mesothelioma cell lines." (PMID 31867277, 2019). "HGF and c-Met are highly expressed in SV40-positive mesothelioma samples." (PMID 25756049, 2015). "Molecular targeting agents that inhibit EGF/EGFR or VEGF/VEGFR pathway such as erlotinib, gefinitib and bevacizumab however failed to produce clinical benefits, but an inhibitor to block the HGF/c-Met pathway has not yet been examined for the efficacy to mesothelioma." (PMID 26191485, 2015).